CBX7 (chromobox 7)
Diseases named in the same sentence as CBX7 in open-access papers (continued):
Sharing a sentence is not in itself a finding about the gene and the disease.
meningioma (continued). "The measurements of ECAR and OCR further confirmed that the CBX7 restoration-induced metabolic switch from glycolysis to OXPHOS was reversed by the overexpression of LDHA, which suggested that CBX7 restoration forces metabolic switch in meningioma cells via repressing LDHA expression." (PMID 37791390, 2024). "Importantly, c-MYC directly binds to the LDHA promoter to activate its transcription in malignant meningioma cells, while CBX7 restoration forces the degradation of c-MYC protein and then attenuates c-MYC-mediated transactivation of LDHA transcription." (PMID 37791390, 2024). "Nevertheless, the role of CBX7 during meningioma progression remains to be elucidated." (PMID 37791390, 2024). "The Kyoto Encyclopedia of Genes and Genomes (KEGG) annotation showed that these differentially regulated genes were mainly enriched in metabolism-related pathways, especially glycolysis and pyruvate metabolism, which indicated that CBX7 restoration may influence glycolysis in meningioma cells." (PMID 37791390, 2024). "Therefore, our results support the tumor-suppressive role of CBX7 during meningioma development." (PMID 37791390, 2024). "The results showed that USP44 overexpression reduced the levels of CBX7-mediated c-MYC ubiquitination in both IOMM-Lee and CH157 meningioma cells." (PMID 37791390, 2024). "Next, we assessed the expression level of CBX7 in a larger cohort with 445 human meningioma samples, including 270 grade I, 112 grade II (atypical), and 63 grade III (anaplastic) meningiomas." (PMID 37791390, 2024). "Altogether, our results shed light on the critical role of CBX7 in meningioma malignancy progression and identify the CBX7/USP44/c-MYC/LDHA axis as a promising therapeutic target against meningioma progression." (PMID 37791390, 2024). "In addition, we only correlated the expression patterns of CBX7, c-MYC, LDHA, and Ki-67 in 445 meningioma patient samples with the follow-up outcomes of these patients." (PMID 37791390, 2024). "Next, we overexpressed c-MYC in meningioma cells with or without CBX7 restoration to determine the functional role of c-MYC in the CBX7/LDHA axis." (PMID 37791390, 2024). "First, we only used two representative malignant meningioma cell lines, IOMM-Lee without NF2 mutation and CH157 with NF2 mutation, to explore the regulation and roles of the CBX7/USP44/c-MYC/LDHA axis." (PMID 37791390, 2024). "To recapitulate the functional role of CBX7 during meningioma progression, we subcutaneously injected IOMM-Lee meningioma cells with or without CBX7 restoration to build the subcutaneous meningioma xenograft mouse model." (PMID 37791390, 2024). "Then, cycloheximide (CHX) was used to block de novo protein synthesis and the protein levels of c-MYC in meningioma cells with or without CBX7 restoration were measured." (PMID 37791390, 2024). "Unexpectedly, c-MYC protein levels were remarkably lower in CBX7-restored meningioma cells than in control cells, while c-Myc mRNA levels in CBX7-restored and control cells were comparable, suggesting that c-MYC protein is post-translationally modified by CBX7 restoration." (PMID 37791390, 2024). "Mechanistically, CBX7 restoration destabilizes c-MYC protein by transcriptionally suppressing USP44 expression and then inhibits the c-MYC-dependent transactivation of LDHA transcription, thus inhibiting glycolysis activity and subsequent cell proliferation in meningioma cells." (PMID 37791390, 2024). "Although another primary meningioma cell line, HSMN1, was used in the animal model and similar phenotypes were observed, we cannot exclude the existence of other unknown confounders that might affect the conclusion regarding the regulation of the CBX7/USP44/c-MYC/LDHA axis." (PMID 37791390, 2024).
meningioma (continued). "Since we did not analyze the transcriptome and chromatin binding patterns of CBX7 or c-MYC in meningioma cells with or without CBX7, we cannot exclude the possibility that c-MYC or CBX7 regulates other pathways to mediate the metabolic switch and inhibit cell proliferation." (PMID 37791390, 2024).
metastasis (1 paper, 2015). The spread or migration of cancer cells from one part of the body (where they first appeared) to another. "Association analysis showed that CC patients with lymph metastasis had lower Cbx7 mRNA levels than their negative counterparts (P = 0.029)." (PMID 25881303, 2015).
ovarian adenocarcinoma (1 paper, 2021). An adenocarcinoma that arises from the ovary. "In a previous study, the CBX7 overexpression has been associated with the poor prognosis of the ovarian adenocarcinomas through inhibiting the TRAIL-induced apoptotic pathway, suggesting the carcinogenic effects of CBX7." (PMID 33748425, 2021).
ovarian tumor (1 paper, 2023). "Having demonstrated the significant impact of CBX7 loss on OC progression, we sought in this study to identify specific mechanisms within the ovarian tumor microenvironment that can regulate its expression." (PMID 38037081, 2023). "In this study, we identified miR-421 as a specific signaling pathway in the ovarian tumor microenvironment that can downregulate CBX7 to induce epigenetic change in OC cells, which can drive disease progression." (PMID 38037081, 2023). "The goal of this study is to identify specific signaling pathways in the ovarian tumor microenvironment that down-regulate CBX7." (PMID 38037081, 2023). "Taken together, our results show that miR-421 is a direct regulator of CBX7, and that adipose-derived exosomes are an important source of miR-421 in the ovarian tumor microenvironment." (PMID 38037081, 2023). "Given that adipocytes are an integral component of the peritoneal cavity and the ovarian tumor microenvironment, we hypothesize that the adipose microenvironment is an important regulator of CBX7 expression." (PMID 38037081, 2023).
prostate tumor (1 paper, 2019). "It is reported that CBX7 and CDKN2B-AS1 levels are enhanced in prostate tumor tissues." (PMID 31572428, 2019).
renal carcinoma (1 paper, 2022). A carcinoma arising from the epithelium of the renal parenchyma or the renal pelvis. "Protein-protein interaction (PPI) network analysis indicated that the E3 ligase RNF26 was closely associated with CBX7 in renal cancer." (PMID 35342353, 2022). "CBX7 loss is a common feature in many cancers, including renal cancer." (PMID 35342353, 2022). "ETS1 was the most changed candidate after CBX7 silencing, and this phenomenon was observed in renal cancer cells." (PMID 35342353, 2022). "Then, we explored the mechanism by which CBX7 regulates the expression of IL6 in renal cancer cells." (PMID 35342353, 2022). "Separate from the transcriptional regulation of CBX7, we focused on the posttranscriptional modification of CBX7 in renal cancers." (PMID 35342353, 2022). "We demonstrated that RNF26 interacted with CBX7 and promoted CBX7 degradation in renal cancer cells, which provides novel insight into the low expression of CBX7 in cancers." (PMID 35342353, 2022). "We further evaluated the relationship between RNF26 and CBX7 in renal cancer cells after knocking down RNF26." (PMID 35342353, 2022). "Here, we demonstrated that CBX7 was another substrate of RNF26 for degradation in renal cancer cells." (PMID 35342353, 2022). "Together, these findings briefly show that CBX7 inhibits the aggressive behavior of renal cancer cells." (PMID 35342353, 2022). "In contrast, elevation of the CBX7 protein and mRNA levels led to reduced proliferation of renal cancer cells." (PMID 35342353, 2022). "IL6 is the downstream gene of TNF signaling 13, and CBX7 contributes to the repression of TNF signaling in renal cancer cells." (PMID 35342353, 2022). "CCK-8 and colony formation assays showed that silencing CBX7 enhanced the growth ability of renal cancer cells." (PMID 35342353, 2022). "We also demonstrated that knockdown of CBX7 promoted renal cancer cell invasion in vitro." (PMID 35342353, 2022). "We also showed that overexpression of CBX7 decreased ETS1 expression in renal cancer cells." (PMID 35342353, 2022). "Moreover, we found that RNF26 functioned as an E3 ligase for CBX7 and promoted CBX7 degradation in renal cancer cells." (PMID 35342353, 2022). "And RNF26 degraded CBX7 to promote the renal cancer cells proliferation." (PMID 35342353, 2022). "Thus, our data indicated that RNF26 regulated the protein stability of CBX7 in renal cancer cells." (PMID 35342353, 2022). "Moreover, Tsin-CBX7 was transduced into renal cancer cells to rescue CBX7 expression." (PMID 35342353, 2022). "In contrast, overexpression of CBX7 reduced the IC50 values of sunitinib and pazopanib in renal cancer cells." (PMID 35342353, 2022). "Then, RNA-seq data for CBX7 indicated that CBX7 inactivated the TNF pathway to block tumor growth and downregulated IL6 to sensitize renal cancer cells to TKIs." (PMID 35342353, 2022). "Analysis of the TCGA-KIRC dataset also revealed that CBX7 was downregulated in renal cancer tissues compared with nontumor renal tissues." (PMID 35342353, 2022). "To further explore the relationship between RNF26 and CBX7 in renal cancer cells, we treated renal cancer cells with or without a 26S proteasome inhibitor (MG132) under conditions of knockdown or overexpression of RNF26." (PMID 35342353, 2022). "Moreover, IHC staining of a renal cancer tissue microarray with anti-CBX7 and anti-RNF26 antibodies demonstrated that CBX7 expression was negatively correlated with RNF26 expression in the patient specimens (Spearman correlation r = -0.349, P = 0.0318)." (PMID 35342353, 2022). "In addition, we also showed that combined knockdown of CBX7 and RNF26 attenuated the tumor growth inhibition effect induced by knockdown of RNF26 alone in renal cancer cells and a subcutaneous xenograft model." (PMID 35342353, 2022). "Moreover, the IHC staining assay of the renal cancer tissue microarray with the anti-CBX7 antibody showed that the protein levels of CBX7 in nontumor tissues were greater than those in renal cancer tissues." (PMID 35342353, 2022).
teratocarcinoma (1 paper, 2012). A germ cell tumor characterized by the presence of an embryonal carcinoma component and a teratoma component. "Interestingly, among the different Pc orthologs, the expression of Cbx7 was clearly associated with pluripotency; we observed that it is highly expressed in ESCs and teratocarcinomas." (PMID 22226354, 2012). "Cbx7 is expressed at high levels in ESCs and teratocarcinoma cells while its levels decrease during differentiation." (PMID 22226354, 2012). "We noted similar changes in Cbx7 expression when 46C ESCs were induced to differentiate into embryoid bodies (EBs) in an independent ESC line (Oct4-GIP ESC), and during retinoic acid-induced differentiation of P19 murine teratocarcinoma cells." (PMID 22226354, 2012).
thyroid tumor (1 paper, 2017). A benign or malignant neoplasm affecting the thyroid gland. "A previous study has indicated that CBX7 overexpression enhanced E-Cadherin activity by interacting with HDAC2 and inhibiting its activity on the E-cadherin promoter in thyroid tumors." (PMID 28388562, 2017).
urinary system tumors (1 paper, 2024). "In urinary system tumors, recent reports have revealed the RNF26/CBX7 axis, where RNF26 promotes the degradation of CBX7, regulating the TNF signaling pathway in ccRCC and promoting ccRCC tumor growth." (PMID 38890443, 2024).
vascular malformation (1 paper, 2024). A non-neoplastic disorder that is the result of defects of vascular morphogenesis. "Hence, the discovery that the PRC1 protein CBX7 is activated in CCM provides yet another hint at a cancer-like molecular mechanism involved in vascular malformations." (PMID 39402138, 2024).
tumor (82 papers, 2010 to 2025). "Although CBX7 plays an important role in multiple cancers, either as an oncogene or tumor suppressor, CBX7 has been rarely found to be mutated in cancer." (PMID 40552137, 2024). "Our group previously reported that CBX7 functions as a tumor suppressor in OC and its loss enhances metastasis in an OC xenograft model." (PMID 38037081, 2023). "For both assessed RCC subtypes, these three CBXs presented a similar profile: CBX3/6/7 showed the highest rates of genetic alteration, CBX3 mRNA level was upregulated, CBX6/7 associated with tumor stage, and CBX7 also associated with better prognosis." (PMID 36292141, 2022). "Otherwise, in the pRCC subtype, CBX2, CBX3, CBX7, and CBX8 were deregulated, and CBX2, CBX6, and CBX7 were associated with the tumor stage." (PMID 36292141, 2022). "We demonstrated that significant upregulation of CBX3 and downregulation of CBX7 are consistently associated with enriched cancer stem-cell-like phenotype across distinct tumor types." (PMID 36361869, 2022). "In our study, CBX6 and CBX7 were favorable prognostic factors for ccRCC, and low CBX6 and CBX7 expression was positively associated with advanced cancer stage and tumor grade in ccRCC patients." (PMID 34395271, 2021). "Ubiquitinated proteins regulate the tumor cell cycle in multiple ways, and the expression of CBX7 was also associated with the cell cycle in tumors." (PMID 34966411, 2021). "The group with higher expression of CBX7, associated with an inhibition of tumor progression, presented larger numbers of infiltrating immune cells." (PMID 34966411, 2021). "High expression of CBX4 was associated with tumor size, pathologic differentiation and poorer survival of patients, while down-regulation of CBX7 was found to be associated with shorter overall survival (OS) of HCC patients." (PMID 30481161, 2018). "Serving as a transcriptional regulator, CBX7 has been implicated in the transcriptional regulation of various oncogenes and tumor suppressors." (PMID 28030829, 2017). "Inhibition of miR-183-5p and miR-182-5p in vitro causes up-regulation of the tumor-suppressive genes CBX7 and EGR1." (PMID 29141042, 2017). "In these samples we found that protein and mRNA levels of CBX7 are also negatively associated with tumor grade." (PMID 28460453, 2017). "Among the underexpressed genes, we observed the DNAm reader ZBTB4, whose expression has been significantly correlated with relapse-free survival, as well as the polycomb component and K36 reader, CBX7, which has already been implicated as a tumor suppressor." (PMID 26169266, 2015). "CBX1, CBX6, and CBX7 were also significantly associated with the tumor stage." (PMID 36292141, 2022). "The effects of miR-181ab1 deficiency on tumour progression were mediated by CBX7." (PMID 35867177, 2022). "The expression of POU5F1, a key regulator of stem cell pluripotency, substantially increased, while the expression of CBX7, a gene that encodes a Polycomb protein which globally regulates cellular lifespan and is a tumor suppressor in both mice and humans, decreased towards ESC/iPSCs." (PMID 35587924, 2022). "The increase of CBX2/3/4/5 and a decrease of CBX7 in comparison to adjacent tissues in GC may be caused by the potential differences in cellular content in tumor vs. adjacent tissues." (PMID 34117289, 2021). "The in silico prediction of CBX7 function was in line with tumor-associated phenotypes." (PMID 28460453, 2017). "Moreover, a direct correlation between the loss of CBX7 expression and a more advanced stage of neoplastic disease and a poor survival has been frequently reported." (PMID 25190058, 2014). "In addition, the tumor-associated role of CBX7 has been studied." (PMID 35342353, 2022). "Subsequent in vitro functional experiments demonstrated that overexpression of CBX7 significantly inhibited tumor sphere growth, and western blot results also showed decreased expression of stemness markers." (PMID 39988672, 2025).
tumor (continued). "To further validate the tumor-suppressive role of CBX7 in vivo, we performed intracranial xenograft tumor growth assays using luciferase-labeled U251 cells and control vectors in nude mice." (PMID 39988672, 2025). "This interaction is significant because CBX7 typically functions as a tumor suppressor, while HMGA1 promotes tumor progression." (PMID 40175347, 2025). "Collectively, the results provide strong evidence that CBX7 acts as a critical tumor suppressor in PDAC." (PMID 40387566, 2025). "To determine the cause of hypermethylation of the CBX7 promoter, we analyzed methylation data from the CGGA database and found that the methylation level of CBX7 was higher in tumor compared to normal tissues." (PMID 39988672, 2025). "Subsequently, we injected CBX7-overexpressing cells into the axillae of nude mice and observed a significant reduction in tumor volume and size in the CBX7-overexpressing group." (PMID 39988672, 2025). "In summary, our study reveals that DNMT1‐mediated methylation of the CBX7 promoter region leads to the downregulation of CBX7 expression in PDAC, which is significantly associated with tumor clinical staging." (PMID 40387566, 2025). "Recently, accumulated evidence has demonstrated that CBX7 plays versatile functions in tumorigenesis; however, the role of CBX7 during tumor development remains inconsistent in different cancers." (PMID 37791390, 2024). "Through log-rank survival analysis, we found that along with tumor grade, tumor location, postoperative radiation, and tumor resection grade, CBX7 served as a positive prognostic factor for both PFS and OS." (PMID 37791390, 2024). "The results demonstrated a gradual decrease in CBX7 expression as tumor pathological grade increased." (PMID 37791390, 2024). "We analyzed the gene mutations of individuals with high and low expression of CBX6 and CBX7, evaluated immune cell infiltration by different immune algorithms in tumor tissue, and then verified the immune infiltration results." (PMID 37189494, 2023). "When tumor tissue exhibited low CBX7 expression, the infiltration of quiescent mast cells (marked by KIT) in the tumor center was significantly inhibited." (PMID 37189494, 2023). "In other studies however, CBX7 has been described as a tumor suppressor and its downregulation has been correlated with aggressiveness and poor prognosis in thyroid, breast and colon cancers." (PMID 38037081, 2023). "We found that TNF pathway inhibitors treatment (IKK-16 and JSH-23) diminished the tumor growth-promoting effect induced by CBX7 knockdown in both 786-O and A498 cells." (PMID 35342353, 2022). "We provide strong evidence that miR-181ab1 promotes tumour progression by inhibiting CBX7, a known miR-181 target and tumour suppressor." (PMID 35867177, 2022). "The expression of CBX genes differs across solid tumors and for CBX1, CBX2, CBX3, CBX4, CBX5, and CBX8 is predominantly upregulated, while for CBX6 and CBX7 is mostly downregulated in tumor tissues." (PMID 36361869, 2022). "Conversely, CBX7 plays as a tumor suppressor and is negatively correlated with cancer aggressiveness." (PMID 35464847, 2022). "In vivo experiments also showed that CBX7 overexpression suppressed tumor growth and Ki-67 (a cell proliferation biomarker) expression." (PMID 35646140, 2022). "In summary, WT tumours showed lower levels of CBX7 expression than miR-181ab1 KO tumours and restored- or over-expressed CBX7 repressed liver tumour progression in WT mice." (PMID 35867177, 2022). "We observed that in all 4 tested tumor types and using several distinct stemness quantifiers, the expression of CBX3 is significantly positively, while the level of CBX7 is significantly negatively associated with cancer stemness in TCGA data." (PMID 36361869, 2022). "We collected CBX7 targets based on whole-genome ChIP-sequencing data and compared these CBX7 target genes with 532 down-regulated genes in KO tumours compared with WT tumours." (PMID 35867177, 2022).